UCN3 (urocortin 3)
Description:
Hormone that plays a central role in whole body adaptation to stress. Released by the hypothalamus primarily in response to physical or psychological stress and acts by binding to CRH receptor CRHR2. UCN3-dependent signaling plays a key role in the metabolic regulation and energy homeostasis in responses to stress, acting as an anxiolytic. Promotes energy balance by reducing food intake, improving insulin sensitivity and managing blood glucose levels in response to metabolic stress (By similarity). In contrast to CRH and UCN, does not activate the hypothalamus-pituitary-adrenal axis to promote corticotropin hormone (ACTH) production.
Synonyms: SPC; UCNIII; SCP
Tractability: Antibody: its Gene Ontology location is reachable by antibodies, with high confidence; UniProt places it where antibodies can reach, with medium confidence; UniProt predicts a signal peptide or a membrane-spanning region.
Gene: Protein-coding gene on chromosome 10 (5,364,966 to 5,374,692, forward strand). Ensembl gene ENSG00000178473.
Subcellular location: Secreted
Pathways (Reactome):
Signal Transduction: Class B/2 (Secretin family receptors)
Gene Ontology:
Molecular function: neuropeptide hormone activity; protein binding; corticotropin-releasing hormone receptor binding; corticotropin-releasing hormone receptor 2 binding; hormone activity
Biological process: general adaptation syndrome; adenylate cyclase-activating G protein-coupled receptor signaling pathway; cellular response to nutrient levels; energy homeostasis; hormone-mediated signaling pathway; positive regulation of insulin secretion; aggressive behavior; cellular response to hypoxia; digestion; positive regulation of membrane potential; response to corticosterone; response to glucose; response to immobilization stress; response to starvation
Cellular component: extracellular region; axon; axon terminus; varicosity
Genetic constraint (gnomAD): Loss-of-function variants: 3 observed, 3.84 expected, observed/expected ratio (o/e) 0.78, 90% interval 0.35 to 1.74. That is too few expected variants to judge how well the gene tolerates losing a copy. Missense variants: 206 observed, 216.35 expected, observed/expected ratio (o/e) 0.95, 90% interval 0.85 to 1.07. Synonymous variants: 100 observed, 98.16 expected, observed/expected ratio (o/e) 1.02, 90% interval 0.87 to 1.2.
Homologues: Orthologues: chimpanzee UCN3 (99% identical), macaque UCN3 (89% identical), rabbit UCN3 (75% identical), dog UCN3 (68% identical), rat Ucn3 (65% identical), mouse Ucn3 (64% identical), tropical clawed frog ucn3 (57% identical), zebrafish ucn3l (44% identical). Paralogues in human: UCN2 (14% identical).
Diseases named in the same sentence as UCN3 in open-access papers:
UCN3 is named in the same sentence as 29 diseases in open-access papers, as found by Europe PMC text mining. Sharing a sentence is not in itself a finding about the gene and the disease. The quoted sentences say what the papers report.
Anxiety (15 papers, 2012 to 2025). Intense feelings of nervousness, tension, or panic often arise in response to interpersonal stresses. "Hence, in mammals, UCN3 is associated with anxiety-like behavior." (PMID 36330212, 2022). "We demonstrate that Ucn3 has the potential to ameliorate anxiety-like behavior in SPS animals and also to affect the neuroendocrine system in the BNST and PVN." (PMID 39595978, 2024). "In the nicotine withdrawal model, ICV administration of Ucn2 and Ucn3 ameliorated anxiety- and depressive-like behavior in mice, but it is important to note that behavioral testing was performed 30 min after the ICV application." (PMID 39595978, 2024). "Gene expression profiles in the amygdala have identified and validated Ucn3 and Tacr3 genes to be involved in fear/anxiety traits in rats." (PMID 38516965, 2024). "Based on these results, we can assume that the IN Ucn3 treatment had a protective effect and prevented the development of anxiety-like behaviors in the animals exposed to SPS." (PMID 39595978, 2024). "Animals with CRHR2 knockout or that of its ligands (Ucn2 KO and Ucn3 KO) display increased anxiety, corticosterone response, and impaired stress recovery." (PMID 39595978, 2024). "Nevertheless, the results obtained from the behavioral tests suggest that IN Ucn3 administration has the potential to prevent the development of anxiety-like behavior in animal models of PTSD." (PMID 39595978, 2024). "Several synthetic bioactive peptides related to urocortin 3, growth hormone-releasing hormone, neuromedin U, and kisspeptin, have antidepressant-like or anxiety-like effects via the receptors for neurotransmitters or the release of neurotransmitters." (PMID 35203663, 2022). "Exposure to TMT during pubertal development delayed puberty, suppressed pre-pubertal LH pulsatility and enhanced anxiety-like behaviour, while activation of MePD Ucn3 neurons reduced LH pulse frequency and delayed puberty." (PMID 35655799, 2022). "Early psychosocial stress exposure decreases GnRH pulse generator frequency delaying puberty while inducing anxiety-behaviour in female mice, an effect potentially involving Ucn3 neurons in the MePD." (PMID 35655799, 2022). "We next investigated the effects of ablation of PeFA Ucn3 neurons on anxiety-like behaviors, responses to a novel object, and burying behavior." (PMID 33385113, 2021). "Nevertheless, there are still no studies investigating the effects of activation and ablation/inhibition of PeFA Ucn3 neurons on anxiety-like behaviors." (PMID 33385113, 2021). "In rodents, central administration or overexpression of urocortin 3 increases stress-induced anxiety and suppresses ingestive behaviour." (PMID 34326416, 2021). "In the present study, we aimed to identify a stimulus activating PeFA Ucn3 neurons and elucidate the behavioral effects of activation/ablation of these neurons, including anxiety-like behaviors." (PMID 33385113, 2021). "Optogenetic activation of LS CRFR2 neurons, a target of PeFA Ucn3 neurons, promoted, whereas inhibition suppressed, anxiety-like behaviors." (PMID 33385113, 2021). "The purpose of the present study was to identify stimuli that activate PeFA Ucn3 neurons and elucidate the behavioral effects of activation and ablation of these neurons, including anxiety-like behaviors." (PMID 33385113, 2021). "For example, overexpression of Ucn3 in the PeFA increased both the respiratory exchange ratio and heat production without affecting food intake in mice, in addition to elevating anxiety-like behaviors." (PMID 33385113, 2021). "Several neuropeptides (neuropeptide Y, isotocin, urocortin 3, prolactin) showed consistent expression patterns with the alleviation of stress and anxiety when anxiety-related behavior was reduced with fluoxetine treatment." (PMID 23706039, 2013). "Mice overexpressing Ucn3 exhibited higher anxiety-like behavior, as evidenced by less time spent on the open arms and less entries made to the open arms of the EPM." (PMID 22704666, 2012).
Anxiety (continued). "Mice overexpressing Ucn3 in the rPFA display increased anxiety, which is most likely through rPFA Ucn3 acting on CRH-R2 neurons in the lateral septum." (PMID 23077729, 2012). "This extends and accords with the previously observed increase in anxiety seen following viral overexpression of Ucn3 in hypothalamus." (PMID 22704666, 2012). "The EPM test was performed to examine whether CRHR2 agonist (Ucn2 or Ucn3) treatment could prevent the development of anxiety-like behavior in the SPS animals compared to the vehicle-treated ones." (PMID 39595978, 2024). "Moreover, they also showed that the central administration of Ucn2 or Ucn3 has the potential to ameliorate anxiety- and depressive-like behavior." (PMID 39595978, 2024). "Our UCN3 data suggest a possible behavioral role of UCN3 in birds related to anxiety." (PMID 36330212, 2022). "First, UCN3 may limit the extent of behavioral response to stress and thus may be beneficial for preventing excessive anxiety, which, in turn, may be an appropriate response to a stressful situation." (PMID 28790894, 2017). "However, in UCN3OE mice, ongoing Ucn3 stimulation of CRFR2 models a chronically stressed animal with increased anxiety-like behaviors and decreased responsiveness of 5-HT1AR autoreceptors." (PMID 22704666, 2012). "In an open field behavioral test in rodents or a dark-light emergence test, mice injected with 20 ng UCN3 intracerebroventricularly (icv) showed significantly less anxiety-like behavior than controls that was associated with no changes in plasma concentrations of ACTH and CORT." (PMID 36330212, 2022). "Second, the behavioral effects of Ucn3/CRFR2 might depend on increased expression of Ucn3, as there are reports demonstrating that stress increases Ucn3 mRNA levels and increased anxiety-like behavior has been reported after overexpression of Ucn3 in PeFA neurons." (PMID 33385113, 2021). "Ucn3 administration to SPS animals increased their locomotor activity and decreased their anxiety-like behavior in the OF test." (PMID 39595978, 2024). "Mice overexpressing Ucn3 display an increase in stress-related behaviors under basal circumstances, suggesting chronic CRFR2 activation promotes an anxiety-like state." (PMID 22704666, 2012). "The activation of CRF1 by the intracerebroventricular (ICV) injection of CRF and Ucn1 evokes the activation of the HPA axis, as well as anxiety-like and depression-like behavior, whereas activation of CRF2 by the ICV administration of Ucn2 and Ucn3 has anxiolytic and antidepressant effects in rats." (PMID 37626714, 2023). "Stressin1-A induced anxiety-like behavior, which was reflected in social interactions, while Ucn3 did not influence social interactions." (PMID 37626714, 2023). "Accumulating evidence has suggested that PeFA Ucn3 and its receptor, CRFR2, play an important role in energy homeostasis and stress-related responses, including anxiety-like behaviors." (PMID 33385113, 2021). "(1999), the behavioral effects of Ucn3/CRFR2 in the LS are affected by stress, thus activation of PeFA Ucn3 neurons in stressed animals may increase anxiety-like behavior, an important experiment for future study." (PMID 33385113, 2021). "In addition, UCN3/CRHR2 possesses a variety of biological effects in the regulation of stress and anxiety, as well as stimulating sympathetic outflow, which was characterized by increased thermogenesis of BAT and upregulated Ucp1 in BAT." (PMID 31379744, 2019). "However, the ICV administration of Ucn1, Ucn2, and Ucn3 in mice, and the global knock-out of urocortins and their receptors led to different results regarding the activation of the HPA-axis, as well as for anxiety- and depression-like behavior." (PMID 37626714, 2023). "Although the LS, a projection target of PeFA Ucn3 neurons, is a regulatory center for anxiety, our results indicated that neither activation nor ablation of PeFA Ucn3 neurons changed anxiety-like behavior." (PMID 33385113, 2021).
diabetes (8 papers, 2013 to 2024). "The decreased expression of UCN3 in pancreatic β-cells in patients with diabetes revealed the loss of this feedback mechanism." (PMID 31781037, 2019). "The disappearance of Ucn3 from β cells that still express high levels of insulin suggests that the loss Ucn3 is an early marker of β cell stress in diabetes, occurring before the reduction in insulin expression." (PMID 25233132, 2014). "Intriguingly, most of the identified genes, which showed strong signals in normal islets but were potently suppressed by STZ, were previously linked with important β-cell functions or diabetes development, such as Slc2a2, Ucn3, Gad1, Cox6a2, Trpm6 and Vdr." (PMID 23828045, 2013). "UCN3 secretion is reduced early in pre-diabetes, with the associated loss of UCN3-stimulated somatostatin release at the delta-cell causing the loss of an important element of rapid paracrine hormone control (such as at the alpha-cells), which will contribute to glycemic instability." (PMID 38612880, 2024). "Although UCN3 is expressed in human adipose tissue, the association of UCN3 with obesity and diabetes remains unclear." (PMID 31781037, 2019). "Our results put the loss of Ucn3 expression as an early event in β cell stress, occurring at the compensatory stage, before reduction in insulin expression and deterioration to frank diabetes." (PMID 25233132, 2014). "STZ treatment also suppressed expression of a wide range of genes linked with key β-cell functions or diabetes development, such as G6pc2, Slc2a2 (Glut2), Slc30a8, Neurod1, Ucn3, Gad1, Isl1, Foxa2, Vdr, Pdx1, Fkbp1b and Abcc8, suggesting global β-cell defects in STZ-treated islets." (PMID 23828045, 2013). "A detailed characterization of insulin signaling pathways under metabolic stress following UCN3 overexpression is planned, and the results are expected to further elucidate the action of UCN3 on adipocytes in the context of obesity and diabetes." (PMID 34341463, 2021). "The neuropeptide urocortin 3 (UCN3) has a beneficial effect on metabolic disorders, such as obesity, diabetes, and cardiovascular disease." (PMID 34341463, 2021). "It has been reported that UCN3 regulates insulin secretion and is dysregulated with increasing severity of obesity and diabetes." (PMID 34341463, 2021). "Nevertheless, we can exclude the significant uptake of UCN3 by SAT owing to diabetes because of the observation of opposite UCN3 profiles in plasma and SAT and the fact that UCN3 mRNA levels paralleled those of protein levels in SAT." (PMID 31781037, 2019). "As expected, animals treated with S961 developed diabetes (reaching blood glucose levels ≥460 mg/dl) and show an increase in insulin staining, while Ucn3 staining was almost completely abolished." (PMID 25233132, 2014). "UCN3 exhibits a possible beneficial activity for metabolic disorders, such as obesity and diabetes." (PMID 34341463, 2021). "We hypothesized that the potential protective role of UCN3 in obesity and diabetes is exercised at least partially by facilitating cellular stress response in the adipose tissue." (PMID 34341463, 2021). "In line with this and contrary to the pattern of circulating UCN3 observed in our study population, we found that UCN3 expression SAT increased with obesity and blunted with T2D in this tissue likewise previous reports showing decreased levels of UCN3 in β-cells people with diabetes." (PMID 31781037, 2019). "Considering the available data on UCN3 and its family members, we hypothesized that UCN3 expression is increased in adipose tissue and blood in obese people and decreased with diabetes and thus affecting the cross talk between the brain and peripheral organs." (PMID 31781037, 2019). "Interestingly, The Odd Ratios (OR) analysis for plasma UCN3 showed that UCN3 levels are more affected by the obesity than diabetes." (PMID 31781037, 2019).
diabetes (continued). "UCN3 might participates in local adaptive inflammation and stress for maintaining tissue homeostasis but this effect might be blunted with excessive and chronic cellular stress, as in diabetes, and reflected by decreased levels of UCN3 in the SAT." (PMID 31781037, 2019). "Lack of UCN3 has been linked to excessive insulin release, contributing to the pathophysiology of diabetes." (PMID 30400826, 2018). "Moreover, association between RANTES as inflammatory mediator and UCN3 was found in the obese subjects with diabetes but not without diabetes." (PMID 31781037, 2019). "However, the role and involvement of circulating UCN3 in diabetes are yet to be elucidated." (PMID 31781037, 2019). "Lack of UCN3 in turn might cause excessive insulin release, contributing to the pathophysiology of diabetes." (PMID 30400826, 2018). "To confirm that loss of Ucn3 is an early marker of diabetes, we divided the diabetic mice from all three models (LepOb/Ob, LeprDb/Db, and Ins2Akita) into groups according to the severity of their diabetes, regardless of the genetic cause." (PMID 25233132, 2014). "It is noteworthy, however, that loss of expression of Ucn3 per se is not a driver of diabetes, but is rather caused by it, as mice homozygous for a Ucn3-null allele are not diabetic, and even show slightly better glucose tolerance under high-fat feeding and aging." (PMID 25233132, 2014). "The role of UCN2 and UCN3 in glucose homeostasis and diabetes is emerging, whereas CRF2, the predominant peripherally expressed receptor, is a key mediator of sexually dimorphic responses in diabetes phenotype." (PMID 32244319, 2020). "Within the overweight group, the significantly high OR (2.24) of circulating UCN3 in individuals with T2D compared with those without T2D supports the involvement of UCN3 in diabetes." (PMID 31781037, 2019). "Although UCN3 is expressed in human adipocytes and adipose tissue, its role in obesity and diabetes has not been reported." (PMID 31781037, 2019). "However, the role of UCN3 in obesity and diabetes is not well-understood." (PMID 31781037, 2019). "Islets lacking UCN3 show increased insulin secretion and the exogenous administration of UCN2 normalized glucose levels in two distinct murine models of diabetes and increased glucose uptake in the skeletal muscles of obese mice." (PMID 32244319, 2020). "Furthermore, also regardless of HNF4A mutation carrier status or diabetes status, the S7 cells displayed the same GSIS kinetics, the same ultrastructural features and the same levels of proteomics-based protein markers of a mature β-cell, including INS, PDX1, NKX6.1, MAFA, GLUT2, UCN3 and others." (PMID 28684784, 2017).
Hyperglycemia (4 papers, 2014 to 2021). An increased concentration of glucose in the blood. "This is further demonstrated by the loss of Ucn3 in S961-treated mice, exposed to insulin resistance and hyperglycemia for only a week." (PMID 25233132, 2014). "Increased expression of UCN3 is thought to protect from high-fat diet-induced hyperglycemia and can increase energy expenditure.Therefore, UCN3 represents a potential therapeutic target for metabolic diseases management." (PMID 31781037, 2019). "In line with this, transgenic UCN3+ mice exhibited a favorable metabolic phenotype resisting obesity and hyperglycemia with improved fatty acid metabolism." (PMID 31781037, 2019). "We can speculate that Ppy-lineage beta cells with low levels of GLUT2 and UCN3 expression may be generated by the pancreas to survive conditions of metabolic stress under hyperglycaemia, at the expense of glucose-induced INS secretion." (PMID 34498099, 2021). "The strong correlation observed between UCN3, TGL, and visfatin in plasma further indicates global metabolic disturbance due to obesity and hyperglycemia in our study population." (PMID 31781037, 2019). "After removal of S961, the expression level of Ucn3-GFP was up-regulated, returning to levels comparable to control animals, corresponding to the remission of hyperglycemia." (PMID 25233132, 2014).